FAP (fibroblast activation protein alpha)
Diseases named in the same sentence as FAP in open-access papers (continued):
Sharing a sentence is not in itself a finding about the gene and the disease.
lung carcinoma (81 papers, 2011 to 2026). "In other types of tumors, high levels of FAP in tumors are associated with poor survival, and in lung cancer, ENO1 is a biomarker associated with patient survival." (PMID 34035230, 2021). "Notably, in lung cancer, as well as in multiple other cancers, FAP-α expressing CAFs have been associated with fibrogenesis and with immune suppression." (PMID 39058055, 2024). "A high level of FAP-expression might be associated with worse prognosis in several cancer types, including lung cancer." (PMID 36428657, 2022). "For example, studies in mice with lung cancer showed that FAPI PET can track the response to FAP CAR-T cell therapy." (PMID 40417720, 2025). "In a study involving 73 patients with lung cancer, FAP expression was observed in 97.3% (71/73) of primary tumors, whereas FDG uptake on PET/CT was positive in 87.7% (64/73) (p = 0.028)." (PMID 40805245, 2025). "For detecting nodal and distant metastases in lung cancer, FAP PET/CT demonstrated superior Sens compared to FDG PET/CT (0.99 [0.90–1.00] vs. 0.77 [0.66–0.85])." (PMID 40805245, 2025). "Elevated FAP expression has been observed in various cancers, including lung cancer, and is correlated with poor prognosis across multiple cancer types." (PMID 40244052, 2025). "The designed retroviral CAR construct specific for the mouse FAP selectively reduces FAPhi stromal cells and inhibits the growth of various murine tumors, namely lung cancer." (PMID 39403603, 2024). "In an A549 lung cancer model, FAP-specific T cells reduced the number of FAP-positive stromal cells and inhibited tumor growth." (PMID 39430235, 2024). "In lung cancer stromal cells, FAP, COL1A1, and COL1A2 exhibited high sensitivity and specificity, reflecting the abundance of fibroblasts and CAFs." (PMID 39034310, 2024). "The markers of COL1A1, COL1A2, and FAP are significantly highly expressed in lung cancer, compared to normal tissues, while PDGFRA, PDGFRB, and ACTA2 either failed to be differentially expressed in cancer tissues, or were expressed in relative lower levels." (PMID 39034310, 2024). "CAFs play a significant role in angiogenesis and metastasis, and FAP is expressed in about 90% of stromal fibroblasts in different cancers, including lung cancer." (PMID 39403603, 2024). "FAPI promising diagnostic performance paved the way also to tailored radioligand therapy (RLT), delivering the therapeutic isotope to the sites expressing FAP, thus enhancing new frontiers for lung cancer therapy." (PMID 39598380, 2024). "FAP’s extensive expression in lung cancer, notably in SCC (100%) and adenocarcinoma (85.7%), has been confirmed." (PMID 38779097, 2024). "This provides a foundation for potential extended investigations about the prognostic significance of FAP in lung cancer." (PMID 39188902, 2024). "Based on previous studies targeting either FAP or integrin αvβ3 for lung cancer imaging with reported advantages 27-30, we synthesized a dual-targeting dimer, [68Ga]Ga-FAPI-RGD." (PMID 37284441, 2023). "It is widely known that FAP is highly expressed in tumor stroma from patients with lung cancer, and FAP overexpression can facilitate the proliferation of CAFs as well as cancer cells in vitro and in vivo." (PMID 37773704, 2023). "Depletion of FAP-positive fibroblasts caused necrosis of both tumor and stroma cells in a transgenic mouse model of lung cancer, which reflected the tumor-promoting function of FAP from another aspect." (PMID 37784082, 2023). "We conducted this pilot exploratory study, based on the notable expression level of FAP and integrin αvβ3 in lung cancer, in a cohort of participants with suspected lung cancer." (PMID 37284441, 2023). "CAFs express fibroblast activation protein (FAP) with studies showing that deletion of FAP resulted in increased collagen deposition and reduced tumor growth in a mouse model of lung cancer." (PMID 34994382, 2022).
lung carcinoma (continued). "Our in vivo data are in line with the data of Klein and colleagues, showing, in murine models of human cancers, such as leukemia, breast or lung cancer, FAP-IL-2v efficacy when combined with therapeutic Ab directed against tumor antigens." (PMID 36230765, 2022). "Of the 114 positive tumors, FAP expression was stromal in 108, epithelial in 1, and mixed in 5 (lung cancer [n = 1], ovarian cancer [n = 1], oropharynx [n = 1], pancreatic [n = 1], and uterine cancer [n = 1])." (PMID 34740953, 2022). "FAPα has been reported to be overexpressed in CAFs in many types of carcinomas, including colorectal, ovarian, breast, bladder, and lung carcinomas." (PMID 36555218, 2022). "Cytotoxic T cell activity was restored, and fast tumour necrosis took place in genetically engineered Lewis lung cancer (LCC) mice when FAPα+ stroma was specifically removed by diphtheria toxin." (PMID 36555218, 2022). "FAP targeted CAR-T cells inhibited the proliferation of TC1 and A549 lung cancer cells by eliminating FAP-positive stromal cells in mice models." (PMID 34790207, 2021). "FAP expression correlates with microvessel density in lung cancer and is induced in stromal cells surrounding newly formed blood vessels in injured cornea." (PMID 34282761, 2021). "Another study discovered that genetic deletion and inhibition of FAP elevated p21 in both an endogenous murine model of lung cancer and a xenograft murine model of colon cancer, and this elevation of p21 possibly occurred via the FAK signaling pathways." (PMID 34068501, 2021). "Supporting this concept, VbP (Talabostat; PT-100; BXCL-701), which exerts potent inhibition of DPP9 and DPP8 and moderate inhibition of DPP4 and FAP, has been shown to lessen tumor burden in lung cancer and sarcoma models." (PMID 33915844, 2021). "In a murine model of mesothelioma and lung cancer, infusion of FAP-CART resulted in growth reduction of the murine tumors in an FAP dependent manner." (PMID 31101063, 2019). "While the levels of FAPα in lung cancer patients, gastric cancer patients and nasopharyngeal cancer patients were similar to the healthy control." (PMID 28415791, 2017). "Markedly over-expression of THBS2 and its co-expressed genes (such as VCAN, CLO11A1, FAP) predicts poor survival of patients with lung cancer; down-regulation of VCAN and THBS2 inhibits cell proliferation in NSCLC." (PMID 28881680, 2017). "Emerging reports showed that MMD, CBX7, FAP played an important role in the proliferation of lung cancer." (PMID 26870998, 2016). "FAP-targeted radiopharmaceuticals are emerging as a promising alternative to FDG, offering greater spec for tumor-associated stromal components across various cancer types, including lung cancer." (PMID 40805245, 2025). "The high heterogeneity of lung cancer may lead to variable FAP expression among different patients, which could explain the inconsistent imaging results observed with FAPI." (PMID 40656546, 2025). "One subtype (MYH11+ α‐SMA+) present in early‐stage lung cancer promotes T‐cell marginalization through the secretion of collagen IV, while the other subtype (FAP+ α‐SMA+) found in late‐stage lung cancer repels T cells through the secretion of collagen XI/XII, exerting an immunosuppressive effect." (PMID 41164803, 2025). "In contrast, FAP‐ CAFs were associated with better prognosis regardless of α‐SMA status in a large lung cancer patient cohort." (PMID 40908670, 2025). "Elevated FAP levels were notable in breast, pancreatic, esophageal, and lung cancers." (PMID 38558814, 2024). "Nonetheless, it is worth noting that FAP may be considered a dependable marker for CAFs in the context of lung cancer." (PMID 39403603, 2024). "FAP is upregulated in lung cancer as well, varying by subtype." (PMID 39598380, 2024). "As described, there are implications that FAP-expression could be used as a prognostic marker in several cancer types, including lung cancer." (PMID 36428657, 2022).
lung carcinoma (continued). "Using FAP-specific PET imaging may allow noninvasive distinction of lung cancer pathological types between SCC, ADC, and SCLC." (PMID 34870727, 2022). "More research on the prognostic value of FAP-expression in lung cancer is needed." (PMID 36428657, 2022). "[18F]AlF-NOTA-FAPI-04 PET/CT imaging revealed differences in FAP expression in metastases of lung cancer, with the highest expression specifically in bone metastases, and thus, may be valuable for distinguishing different pathological types of lung cancer." (PMID 34870727, 2022). "Considering that SHH is activated by FAP overexpression in A549 adenocarcinoma and SK-MES-1 SCC lung cancer lines, it can be inferred that FAP might play an indirect role in the EMT process through SHH/GLI regulation." (PMID 34068501, 2021). "Co-culture of cancer cells with FAP+ CAFs promote migration and invasion, which could be reduced by anti-FAP antibody in lung cancer cells." (PMID 34035230, 2021). "In recent studies, FAP has been considered a target for therapeutic intervention in lung cancer." (PMID 33808627, 2021). "We next assessed whether the accumulation of FAP-targeted-T cells observed in ICO15K-FBiTE-treated mice could improve the antitumor efficacy in A549 (human lung cancer) and HPAC (human pancreatic) tumor models." (PMID 30683154, 2019). "A similar effect was reported from CAR T cell targeted FAP; a treatment with the FAP-CAR T cells resulted in ~80% depletion of FAP+ cells, which was associated with a significant inhibition of tumor growth (35–50%) in mesothelioma and lung cancer mouse models." (PMID 29682521, 2018). "Interestingly nineteen patients underwent static and dynamic 68Ga-FAPI-46 PET in addition to FDG in order to characterise lepidic lung cancer as a known FDG–negative target, and FAP IHC of 24 tissue sections of lepidic lung cancer surprisingly revealed strong FAP positivity in all specimens." (PMID 39598380, 2024). "CARTs targeting fibroblast activation protein-α (FAP), a tumor stromal-associated antigen expressed by CAFs, delivered in combination with an EphA2-targeting CAR population was shown to control the tumor growth in an A549 lung cancer model more effectively than either agent alone." (PMID 30386740, 2018). "A meta-analysis reported Sens of 0.98 (95% CI, 0.88–1.00) for FAP PET/CT and 0.99 (0.74–1.00) for FDG PET/CT in the diagnosis of lung cancer." (PMID 40805245, 2025). "A dual-targeting radiotracer designed to target both FAP expression on CAF and integrin αvβ3 expression on tumor neovasculature has been proposed to enhance the Sens and spec of lung cancer detection." (PMID 40805245, 2025). "FAP-targeted radiopharmaceuticals labeled with 177Lu, 90Y, or 225Ac have demonstrated promising potential for RLT in various malignancies, including lung cancer." (PMID 40805245, 2025). "As in primary tumors, myMAFs are the most abundant subtype, and either α‐SMA+, FAP+, or α‐SMA+/FAP+ myMAFs have been reported in brain metastasis from numerous cancer types, including lung carcinomas." (PMID 40908670, 2025). "In an international multicenter retrospective analysis, 71 patients with various types of cancers, including 9 lung cancer patients, were treated with both 18F-FDG and 68Ga-labeled FAP inhibitors." (PMID 40244052, 2025). "Research on several antigens, including c-MET, DLL3, FAP, and B7-H3 (CD276), has been conducted concerning lung cancer treatment." (PMID 38694508, 2024). "A study using FAP-specific CAR-T cells demonstrated their ability to recognize and eliminate FAP-positive cells, leading to decreased tumor growth in an A549 lung cancer model." (PMID 38516299, 2023). "211At-FAPI(s) and piperazine (PIP) linker FAPI exhibited distinct FAP selectivity and uptake in FAPII-overexpressing HEK293 cells and the lung cancer cell line A549." (PMID 37240044, 2023).
lung carcinoma (continued). "A similar approach was applied for lung cancer by pooling EphA2-targeting CAR-T cells against tumor cells and fibroblast activation protein-α (FAPα)-targeting CAR-T cells against FAP+ stromal cells." (PMID 36717905, 2023). "Another study on murine models of lung carcinoma and PDAC revealed that the deletion of FAP led to a significant reduction in CAF infiltration and tumor tissue necrosis, and an increase in infiltration of CD8+ T cells." (PMID 34094963, 2021). "As a principle source of CXCL12, FAP+ CAFs also use the CXCL12-CXCR4 interaction to inhibit the infiltration of T cells in PDAC and lung carcinoma bearing mice." (PMID 31462327, 2019). "We found that ADSCs treated with lung cancer cell CM expressed the myofibroblast markers α-SMA and FAP." (PMID 31196220, 2019). "They showed activation of endogenous CD4+ T-cells after three days of anti-FAP CAR treatment in an immune-competent syngeneic mouse model of mesothelioma and lung cancer." (PMID 28331617, 2017). "MAFs in lung cancer brain metastasis can express α‐SMA, FAP, and, to a lesser extent, both markers." (PMID 40908670, 2025). "Further in lung cancer tissues, through scRNA analysis at “IMMUcan SingleCell RNAseq-Database” of lung cancer, for the first time, we proved the specificity of COL1A1, COL1A2, and FAP, all of three are highly enriched in subgroup of CAF, the cluster of which was circled." (PMID 39034310, 2024). "Analyzing the expression patterns of CAF markers in lung cancer tissues compared to normal tissues, we found that COL1A1, COL1A2, and FAP were significantly upregulated, indicating their potential as markers for identifying malignancies and metastatic diseases." (PMID 39034310, 2024). "In canine mast cell tumors as well as in human pancreatic adenocarcinoma, colon or lung cancer FAP is known to be a negative prognostic factor." (PMID 37727209, 2023). "No previous studies have stained for both FAP and integrin receptors and investigated the differences in their expression and correlation of expression with different stages of lung cancer." (PMID 37284441, 2023). "In addition, we found that FAP-positive tumor stroma appeared in the ABC1 lung cancer of the NSG mouse model, and our previous study has proven the safety and effectiveness of FAP-targeted CAR-T cells in this mouse model." (PMID 36479116, 2022). "Moreover, western blot analysis of FAP, another myofibroblast marker, and α-SMA expression in epidural ADSCs treated with four types of lung cancer cell CM for 2 days revealed that CM treatment markedly elevated α-SMA and FAP expression in epidural ADSCs." (PMID 31196220, 2019). "However, Kakarla and colleagues using a FAP-CAR with a different scFv demonstrated antitumor efficacy without toxicities in a mouse model of human lung cancer." (PMID 28331617, 2017). "Anti-FAP immunohistochemistry (IHC) staining was thus performed on sections of lung biopsies from WHWTs affected with CIPF, dogs with lung cancer and dogs without pulmonary disease." (PMID 39188902, 2024). "We hypothesized that FAP is expressed in lungs of WHWTs affected with CIPF, as well as in the stroma of canine lung cancers, used as positive controls, but not in healthy lungs." (PMID 39188902, 2024).
ovarian carcinoma (62 papers, 2014 to 2025). A malignant neoplasm originating from the surface ovarian epithelium. "FAP expression in epithelial ovarian cancers is associated with resistance to platinum-based chemotherapy, shorter time to recurrence, and overall worse clinical outcomes." (PMID 37370912, 2023). "FAP overexpression in CAFs has been linked to resistance to therapy in several solid cancers, such as colorectal, pancreatic, gastric and ovarian cancer, highlighting the importance of stromal components in determining outcome." (PMID 34525114, 2021). "Increased expression of FAP is believed to cause recurrence of epithelial ovarian cancer after chemotherapy." (PMID 33109151, 2020). "Multiple FAP-directed imaging agents have demonstrated high tumor-to-background ratios of accumulated activity and excellent diagnostic performance, also for the imaging of ovarian cancer." (PMID 41466165, 2025). "The FAP protein is a serine protease with endopeptidase activity and has been associated with poor prognosis in various tumors, such as breast, colorectal, oral, lung, and ovarian cancer." (PMID 38606999, 2024). "Furthermore, FAP overexpression in colorectal, pancreatic and ovarian cancer is associated with an increased risk of lymph node metastasis and worse prognosis." (PMID 34525114, 2021). "FAP is expressed in the stroma of more than 90% of human cancers of epithelial origin, and its overexpression has been associated with poor prognosis in multiple cancer types, including pancreatic, hepatocellular, gastrointestinal cancers and ovarian cancer." (PMID 29938002, 2018). "Although previous studies illustrated that FAP could promote cancer cells proliferation and invasion in various malignancies, for instance HO-8910 PM ovarian cancer cells, the TME-derived causations were ignored." (PMID 30419872, 2018). "Based on expression of 21 CAF‐associated markers, we defined four subtypes of CAFs in ovarian cancer as follows: myofibroblast CAFs (myCAFs, 0: SMA+, 1: FAP+, 2: COL1A1+) and antigen‐presenting CAFs (apCAFs, 3: CD74+/HLA‐DRA+)." (PMID 40126173, 2025). "Although future validation is needed, lower physiological FAP accumulation in ovaries both in pre- and post-menopausal women, underscores the diagnostic potential of FAPI-PET in ovarian cancer." (PMID 40604259, 2024). "In gastric cancer, glioblastoma, and ovarian cancer, overexpression FAP is correlated with poor survival prognosis." (PMID 39055892, 2024). "FAP is often highly expressed in the stroma of ovarian cancers and has an important role in the proliferation, invasion, and migration of ovarian cancer cells." (PMID 38505595, 2024). "The consistent presence and overexpression of FAP in CAFs across numerous epithelial tumors, including colon, pancreatic, hepatic, and ovarian cancers, have paved the way for targeted FAP approaches in tumor imaging and therapy." (PMID 38543239, 2024). "FAP, as a cell surface serine protease, has been reported to interact with integrin α3β1 and the uPAR signaling complex, mediating ovarian cancer cell migration." (PMID 37919739, 2023). "Further studies found that FAP is critical for ovarian cancer cell survival by sustaining NF-kB activation through recruitment of PRKDC in lipid rafts." (PMID 38063927, 2023). "Several preclinical studies have demonstrated FAP expression in a vast majority (>90%) of ovarian cancers with negligible expression in normal ovarian tissue, benign and borderline tumors." (PMID 37370912, 2023). "Markedly strong FAP expression in terms of malignant cells was determined in two patients diagnosed with epithelial ovarian cancer and leiomyosarcoma of the uterus, which also presented FAP expression within the stroma and angioinvasion." (PMID 34050777, 2021). "In ovarian cancer, FAP was also highly expressed in cancer cells compared to normal epithelial cells." (PMID 34035230, 2021).